TNF (tumor necrosis factor)
Diseases named in the same sentence as TNF in open-access papers (continued):
Sharing a sentence is not in itself a finding about the gene and the disease.
nephritis (continued). "This study has demonstrated that high-dose CS-DMY-NPs significantly regulated the release of IL-1β, TNF-α, and IL-6 in the kidneys of mice, suggesting that DMY may attenuate LPS-induced acute kidney inflammation injury." (PMID 39330225, 2024). "Inflammatory mediators, such as tumor necrosis factor-alpha (TNF-α) and interleukin-1 (IL-1), may enter the bloodstream and affect renal tissues, inducing kidney inflammation and damage." (PMID 38832490, 2024). "In conclusion, we speculateed that SHP may ameliorate nephritis by regulating the AGE-RAGE, IL-17 and TNF signaling pathways." (PMID 37361210, 2023). "Our results demonstrated that TNF, AKT1 and PTGS2 might be the key targets of SHP in the treatment of nephritis." (PMID 37361210, 2023). "Similarly, in response to anti-GBM induced nephritis, EMRMs had higher CD86 expression and TNF production than BMRMs at 2 and 24 h after anti-GBM serum injection." (PMID 32385245, 2020). "TNF-α can induce monocyte chemoattractant protein-1 (MCP-1) expression in mesangial cells, resulting in macrophage recruitment and accumulation in glomerulus, exacerbating kidney inflammation." (PMID 26770985, 2016). "Besides, the patients with nephritis were in the inflammatory status, and inflammation acted as an influencing factor has been clarified by many studies, which found that Scys-C was associated with many inflammatory markers like IL-6, TNF-α but not with C-reactive protein (CRP)." (PMID 24465871, 2014). "Reactive free radical species–mediated oxidative stress may lead to the infiltration of inflammatory cells and increase the mRNA expression of inflammatory genes such as TNF-α, IL-6, NF-кB, and TGF-β, which are all participate in the progression of kidney inflammation in 2K1C rats." (PMID 39886537, 2025). "Among these cytokines, TNF-α was significantly higher than that of HSP patients without nephritis." (PMID 33036556, 2020). "Furthermore, patients with lupus nephritis had higher levels of plasma TNF-α than those without nephritis." (PMID 31409832, 2019). "In addition, hMSCs decrease TNF-a production in immature DCs, which is consistent with the present result that hMSCs significantly decreased TNF-αmRNA expression in renal cortex concomitant with glomerular macrophage reduction in nephritis." (PMID 23826305, 2013). "Thus, the regulation of TNF, AKT1 and PTGS2 may contribute to the treatment of nephritis." (PMID 37361210, 2023). "However, in NZBWF1 mice with established nephritis, TNF-α replacement showed no beneficial effect and could even accelerate disease progression." (PMID 26441980, 2015). "As nephritis progresses, the SGLT2 accumulates without being metabolized due to renal dysfunction and proinflammatory cytokines like IL-6 and TNF-α induce SGLT2 expression in diabetic kidneys." (PMID 34425759, 2021). "The gene expression levels of TNF-α, IL-1β, MCP-1, and IL-6, which are known as proinflammatory cytokines, were much higher in the WKY-HBSS rats than in WKY rats without nephritis." (PMID 23826305, 2013). "It has also been reported that, despite levels of antibodies to ds-DNA and cardiolipin being increased, anti-TNF-α therapy did not exacerbate SLE itself but rather achieved a reduction in disease activity and relief of refractory arthritis, nephritis, etc.." (PMID 23216789, 2012).
renal failure (78 papers, 2007 to 2025). "For example, CD14 was associated with mortality/survival and multiple organ failure; HMOX1 was associated with kidney failure and respiratory failure; TNF was associated with mortality/survival and respiratory failure." (PMID 40168842, 2025). "Relevant literature have shown that IL6, AKT1, VEGFA, FN1, TIMP1, ALB and TNF are associated with renal insufficiency." (PMID 36209090, 2022). "Activation of TNF pathways are associated with kidney disease progression in subjects with renal insufficiency." (PMID 35846341, 2022). "Age, plasma TNF-α, and 8-OHdG are independent risk factors for renal insufficiency in T2DM patients with normoalbuminuria." (PMID 31637265, 2019). "In this study, we found that age, plasma TNF-α, and 8-OHdG were independent risk factors for renal insufficiency in T2DM patients with normoalbuminuria." (PMID 31637265, 2019). "These metabolites significantly inhibit the expression and release of inflammatory cytokines (e.g., TNF-α, IL-1β, and IL-6) induced by podocyte injury, which helps improve renal insufficiency caused by podocyte dysfunction and prevents renal parenchymal damage." (PMID 41194878, 2025). "Although we assessed at least 30% decline in eGFR as a valid surrogate end point for CKD progression, due to the low number of incident kidney failure requiring kidney replacement in this cohort, we were unable to examine the association of incident TNF inhibitor use with a tangible kidney outcome." (PMID 38625700, 2024). "Despite treatment with corticosteroids and anti-TNFα, his kidney function deteriorated, leading to kidney failure and dialysis." (PMID 40932502, 2025). "TNF-α levels were increased in mice with Cis-induced renal toxicity, and TNF-α inhibition or knockdown significantly alleviated Cis-induced renal insufficiency and injury, suggesting that heightened TNF-α production is a key factor in Cis-induced AKI." (PMID 38005304, 2023). "For instance, patients with renal failure generally have higher expression levels of TNF-α than healthy patients." (PMID 38002263, 2023). "The levels of IL-8, MIP-1α, and TNF-α were significantly higher in patients with renal insufficiency." (PMID 32587468, 2020). "Serum TNF-α level of diabetic patients with kidney failure exhibited a significant increase when compared with that of patients with either DM or kidney failure." (PMID 33442388, 2020). "Renal TNF-α expression is increased in a cisplatin-induced nephrotoxic mouse, and cisplatin-induced renal insufficiency and injury can be significantly alleviated by TNF-α inhibition or knockout, indicating that increased TNF-α expression plays an important role in cisplatin-induced nephrotoxicity." (PMID 33750909, 2021). "Therefore, TNF-α can serve as an important indicator in the progression of kidney injury and has been regarded as an attractive target of inflammatory cytokines in developing novel therapeutic agents for kidney failure." (PMID 38002263, 2023). "Key inflammatory pathways, such as PI3K/AKT, JAK/STAT3, TLR/NF-κB, TNF-α, TGF-β1, can exacerbate structural damage in the kidneys of DN patients, ultimately contributing to renal insufficiency." (PMID 40181946, 2025). "Eleven patients had renal insufficiency, with ≥2 mg/dl creatinine; these patients demonstrated significantly higher levels of IL-8, MIP-1α, and TNF-α than those with <2 mg/dl creatinine (p = 0.027, p = 0.013, and p = 0.020, respectively)." (PMID 32587468, 2020). "Our previous study confirmed that the level of TNF-α was increased in T2DM patients, and the current study showed levels of plasma TNF-α and IL-6 were elevated in T2DM patients with renal insufficiency and were inversely related to the eGFR." (PMID 31637265, 2019). "These cells are more common in patients with kidney failure, express high levels of adhesion molecules CD2, LFA-1, and VLA-4, downregulate CD28, and produce IFNγ, tumor necrosis factor alpha (TNFα), and granzyme B consistent with effector/memory phenotype." (PMID 28293238, 2017).
renal failure (continued). "As pointed out above, higher levels of NO and TNF-α at diagnosis of SBP and during SBP episodes predict complications such as renal insufficiency and survival." (PMID 23527251, 2013). "Besides the two most important indicators for prediction of kidney failure, ALP, urea nitrogen and TNF-alpha concentrations in serum also showed remarkably increase, suggesting pathological changes of rat kidney." (PMID 27210744, 2016). "Concomitant with these effects on serum TNF-α, IFN-γ, and IL-6 levels, HOMA-IR and HOMA-IS, the CRP (marker of inflammation) was most deleteriously affected in nephrotic diabetic patients without kidney failure." (PMID 33442388, 2020).
cytomegalovirus infection (77 papers, 2013 to 2026). A herpesvirus infection caused by Cytomegalovirus. "In in vitro studies, CMV infection of villous cytotrophoblasts has been shown to cause a rapid loss of neighboring trophoblasts through apoptosis mediated by tumor necrosis factor α (TNF-α) secretion." (PMID 33374185, 2020). "Treatment of CMV-infected cell cultures with anti-TNF-α antibody and epidermal growth factor completely inhibited CMV infection-induced trophoblast apoptosis and cell loss." (PMID 33374185, 2020). "HCMV infection in primary CTBs led to the rapid loss of bystander cells mediated by HCMV IE1-induced tumor necrosis factor (TNF)-α secretion." (PMID 31569508, 2019). "Assessment of the contribution from TNF (and other innate cytokines) to other programmed cell pathways, including associated with CMV infection including intrinsic apoptosis and necroptosis, is necessary to fully resolve the host–pathogen interaction profile for this virus." (PMID 33126536, 2020). "Cytomegalovirus infection also increases the loss of trophoblasts through apoptosis mediated by TNF-α secretion, which could lead to placental villitis and IUGR." (PMID 33374185, 2020). "Our observations on TNF remains relevant to HCMV infection and associated pathologies." (PMID 33126536, 2020). "In addition to CRP, the proinflammatory cytokines TNF and interleukin-6 (IL-6) are secreted in response to HCMV infection and are independently associated with mortality due to CVD." (PMID 29752343, 2018). "Human cytomegalovirus (HCMV) infection also induces the production of proinflammatory cytokines in inflammatory cells, including IL-1β, IL-6, IL-12, TNF-α, interferon-α/β and IFN-γ." (PMID 39459871, 2024). "PIAS1KO cells were significantly more sensitive to TNFα and IFNα with respect to their ability to limit WT HCMV infection relative to ntg controls." (PMID 38768227, 2024). "Regulation of TNFα-induced cytokine responses and NK inhibition during HCMV infection were dependent on this impairment of ADAM17." (PMID 37561786, 2023). "TNF signaling pathway, toll-like receptor signaling pathway and human cytomegalovirus infection also connect with 3 diseases, including tumors, immune diseases and neurodegenerative diseases." (PMID 35702766, 2023). "Consistent with this possibility, inhibition of O-linked glycosylation phenocopied glycolytic inhibition in that it prevented TNFα-mediated inhibition of HCMV infection, highlighting the importance of glycosylation to TNFα’s anti-viral activity." (PMID 35834576, 2022). "As expected, control ntg cells pretreated with TNFα in the presence of the glycolytic inhibitor 2DG are more permissive to HCMV infection compared to cells pretreated with TNFα alone." (PMID 35834576, 2022). "The figure shows that there are eight main areas of enrichment, including “TNF signaling pathway” and “Human cytomegalovirus infection"." (PMID 36531223, 2022). "When all infants were analysed together, the only TLR agonist/cytokine combination affected by HCMV infection was a lower TNF-α to HKLM stimulation in the HCMV infected as compared to the uninfected group (p = 0.04 unadjusted, 0.066 adjusted)." (PMID 32707906, 2020). "Other cytokines and chemokines that are upregulated during CMV infection of trophoblasts include TNF-α and monocyte chemoattractant protein-1 (MCP-1)." (PMID 33374185, 2020). "KEGG enrichment analysis indicated that C1 was enriched in human cytomegalovirus infection, transcriptional misregulation in cancer, proteoglycans in cancer, TNF signaling pathway and NF-kappa B signaling pathway." (PMID 32874774, 2020). "This is interesting because HCMV infection seemed to lead to lower pro-inflammatory (TNF, IL1β, eotaxin, GMCSF) and Th2 (IL-4) reactivity to general T cell stimulation and the mycobacterial antigen PPD as compared to the HCMV- infants." (PMID 32582177, 2020).
cytomegalovirus infection (continued). "The present study supports that HCMV infection plays an important role in EH pathogenesis through increased TNF-α and 8-OHDG levels, and decreased eNOS and renin levels." (PMID 29752343, 2018). "In patients with EH specifically, CRP, TNF-α, NOX4, 8-OHDG, eNOS, and Ang II were associated with HCMV infection in all models (P<0.05)." (PMID 29752343, 2018). "TLR2, TRL3, and TLR9 were determined as inducing the expressions of IFN-β and tumor necrosis factor alpha (TNF-α) at early times during HCMV infection in human THP-1 cells, as well as in human foreskin fibroblasts (HFF)." (PMID 30241345, 2018). "Analysis of multi-functional T-cell responses by intracellular staining for both human IFNγ and human TNFα indicates that HCMV-infected huBLT mice generate poly-functional T-cells in response to HCMV infection." (PMID 28428537, 2017). "We found that the knockdown of CD147 expression in HFF cells decreased the activation of IFNB1 and interferon-stimulated ISG15 gene expression induced by HCMV infection, as well as expression of the NF-κB downstream genes IL-6 and TNF-α." (PMID 29194430, 2017). "Luminescence measurements demonstrated a trend of SCF promoter activation upon stimulation with RANKL, TNFα, rAD-pp71 expression, or HCMV infection." (PMID 23861869, 2013). "Interestingly, IL-12 has been shown to be required for expansion of adaptive NK cells in response to murine cytomegalovirus infection, while a stimulatory effect of TNFα and potential inhibition of cytotoxic activity of NK cells by IL-6 has been reported." (PMID 40473838, 2025). "Given that PIAS1KO cells were sensitized to TNFα treatment, an inflammatory stimulus, we hypothesized that PIAS1KO cells may be more sensitive to the pro-inflammatory signaling associated with HCMV infection." (PMID 38768227, 2024). "Interestingly, increased HCMV infection upon activation of STING or stimulation with TNF at the time of virus exposure was also observed in other cells of the myeloid lineage such as macrophages." (PMID 38409141, 2024). "The central protein TNF is enriched in several major KEGG pathways, including Kaposi sarcoma-associated herpesvirus infection, human cytomegalovirus infection, and the toll-like receptor signaling pathway, and is a key cytokine that regulates the immune response and inflammation." (PMID 39568580, 2024). "In exploring the finding that HCMV infection up-regulates tumor necrosis factor receptor 2 (TNFR2), a ligand for the pro-inflammatory antiviral cytokine TNFα, we found that the underlying mechanism was due to targeting of the protease, A Disintegrin And Metalloproteinase 17 (ADAM17)." (PMID 37561786, 2023). "KEGG analysis showed enrichment in the cytokine−cytokine receptor interaction, viral protein interaction with cytokine and cytokine receptor, chemokine signaling pathway, human cytomegalovirus infection, ferroptosis, TNF signaling pathway, and FOXO signaling pathway." (PMID 36704339, 2022). "Given that TNFα is broadly anti-viral, we next sought to determine if TNFα’s effects on glycolysis were specific to limiting HCMV infection, or if a similar phenotype could be observed in the context of evolutionary divergent viruses." (PMID 35834576, 2022). "Pathway analysis of targets of DEHMs showed that the upregulated target genes were associated with pathways such as miRNAs in cancer, proteoglycans in cancer, apoptosis pathway, Rap1 signaling, TNF signaling, human cytomegalovirus infection, and fluid shear stress." (PMID 35562533, 2022). "Indeed, several reports have indicated the effectiveness of an anti-tumor necrosis factor-alpha (TNFα) treatment in patients with an active UC and concomitant HCMV infections." (PMID 32244555, 2020). "Active HCMV infection may aggravate the inflammatory microenvironment by increasing production of inflammatory factors such as viral IL-10, tumor necrosis factor-α, transforming growth factor-β and prostaglandins." (PMID 32322296, 2020).
cytomegalovirus infection (continued). "Second, IFN-γ production and TNF-α production were dependent on HCMV infection." (PMID 29038280, 2018). "Notably, patients with EH, particularly those with HCMV infection, exhibited a marked increase in tumor necrosis factor-α (TNF-α) and 8-hydroxy-2-deoxyguanosine (8-OHDG) levels, but a decrease in endothelial nitric oxide synthase (eNOS) and renin levels." (PMID 29752343, 2018). "In addition, our previous studies have also confirmed that HCMV infection inhibits tumor necrosis factor-α induced apoptosis." (PMID 25120656, 2014). "However, upon stimulation by either HCMV infection or TNFα, cytokine signaling genes were strongly induced, partially phenocopying ΔUL26 infection, indicating that the lack of PIAS1 strongly potentiates anti-viral gene expression in the face of an inflammatory challenge." (PMID 38768227, 2024). "The most important protein targets based on its degree from the C-T-P-D network were TNF, MAPK1, MAPK3, IL6, IL1B, AKT1 and CASP3 and the most important pathways associated with these protein targets were “Pathways in cancer”, “IL-17 signaling pathway”, and “Human cytomegalovirus infection”." (PMID 36591238, 2022). "In fact, IL-6 and TNF-α levels in HCMV infected patients’sera are significantly higher, and the high level of IL-6 may indicate a higher risk of HCMV infection, thus being beneficial for early diagnose of HCMV infection." (PMID 25088288, 2014). "Two hundred three signal pathways were enriched after KEGG analysis and the main items included TNF signaling pathway, IL-17 signaling pathway, PI3K-Akt signaling pathway, apoptosis, human cytomegalovirus infection, and Epstein-Barr virus infection." (PMID 39465738, 2024). "To investigate the immunomodulatory effects of treatment with Tα1 + PCDs in CD4+ and CD8+ T cells during HCMV infection, we evaluated the expression of CD2 and CD40L, as well as the production of TNFα, IFNγ and IL-2 using multiparametric cytometry." (PMID 38396631, 2024). "TNF-α, IL-6, and IL-1β at 24–28 weeks of gestation were significantly higher in women with GDM and HCMV infection than inthe other groups (all P < 0.01)." (PMID 35186501, 2022). "In particular, HCMV infection led mainly to the over-expression of CCL2, CCL3, CCL11, CXCR4, IL-1β, IL13, MMP1, MMP3, MMP9 and MMP13, SERPINA1, TNFα, and BMP7, and the gradual and constant downregulation of IL13RA2 (up to almost 800-fold at 14 days p.i.)." (PMID 32899126, 2020). "Inflammatory factors including Tumor Necrosis Factor (TNF)-alpha, interleukin-6 (IL-6), and nitric oxide synthase 2 are produced by M1 macrophages following HCMV infection." (PMID 30081496, 2018). "In the present study, the mRNA of TLR2 and its downstream inflammatory factor, TNF-α, were upregulated with the increased expression of IE1–72 in SW480 cells following HCMV infection." (PMID 25435993, 2015). "Pertinent to this study, it has been shown in the context of HCMV infection that Th1 type gB specific CD4+ T cells that secrete IFNγ and TNFα have also been shown to be able to mediate MHC class II restricted cytotoxicity." (PMID 24130479, 2013). "KEGG enrichment analysis suggested that TNF signaling pathway, IL-17 signaling pathway, PI3K-Akt signaling pathway, apoptosis, human cytomegalovirus infection, and Epstein-Barr virus infection were the main pathways for the core herb combination to treat CVA in children." (PMID 39465738, 2024). "However, we observed lower instead of higher levels of IFN, TNF and ISG expression with the mutant relative to the wild-type protein upon hCMV infection." (PMID 32365141, 2020). "Transcriptomic analysis revealed that HCMV infection dampened the regulatory pathways of interferon gamma (IFN-γ), tumor necrosis factor alpha (TNF-α), and interleukin-1 (IL-1), consequently abrogating the immune responses to M. massiliense coinfection in macrophages." (PMID 33013921, 2020).